MIR4471 (microRNA 4471)
Synonyms: hsa-mir-4471
Gene: MicroRNA gene on chromosome 8 (100,382,763 to 100,382,845, forward strand). Ensembl gene ENSG00000265599.
Diseases named in the same sentence as MIR4471 in open-access papers:
MIR4471 is named in the same sentence as 1 disease in open-access papers, as found by Europe PMC text mining. Sharing a sentence is not in itself a finding about the gene and the disease.
MIR4471 shares sentences with these, for which no sentence is quoted: Esotropia (1 paper).